INS (insulin)
Diseases named in the same sentence as INS in open-access papers (continued):
Sharing a sentence is not in itself a finding about the gene and the disease.
type 2 diabetes (continued). "These pathways are valine, leucine and isoleucine degradation, cell cycle, glycolysis/gluconeogenesis, type II diabetes mellitus, fatty acid metabolism, JAK-STAT signaling, calcium signaling, insulin signaling, Wnt signaling, PPAR signaling, adipocytokine signaling, and Notch signaling pathways." (PMID 37529091, 2022). "Type 2 diabetes is a chronic condition in which the pancreas does not produce enough insulin, and cells respond poorly to insulin and use less sugar." (PMID 35808386, 2022). "In patients with or without type 2 diabetes, efruxifermin treatment has consistently improved markers of glucose metabolism and insulin sensitivity while restoring a healthy lipoprotein profile without increasing body weight." (PMID 36644237, 2022). "Studies assessing HLA, PTPN22 and INS in LADA, type 1 and type 2 diabetes." (PMID 36034444, 2022). "Furthermore, using a CRISPR screen for insulin regulatory genes in MIN6 cells, 17 of the obesity- or type-2-diabetes-affected beta cell genes were found to regulate intracellular insulin content." (PMID 35482056, 2022). "We do not suggest continuous glucose monitoring rather than self-monitoring blood glucose in patients with type 2 diabetes on basal–bolus insulin therapy." (PMID 35288805, 2022). "Type 2 diabetes mellitus (T2DM) is a chronic heterogeneous metabolic disease and a current major global health concern, characterised by increased blood glucose levels driven by insulin resistance in target tissues and pancreatic β-cell dysfunction." (PMID 35628465, 2022). "Several large studies in youth-onset type 2 diabetes have occurred in recent years, including the SEARCH for Diabetes in Youth study, the TODAY (Treatment Options for type 2 Diabetes) study and RISE (Restoring Insulin Secretion) study." (PMID 37990723, 2022). "We aimed to assess long-term efficacy and safety in inadequately controlled type 2 diabetes (T2DM) of two SGLT-2 inhibitors: empagliflozin (Empa) and dapagliflozin (Dapa), combined with metformin, other oral antidiabetics or insulin, according to the protocols in Romania." (PMID 35885680, 2022). "Type 2 diabetes often appears in older adults due to that pancreas does not make enough insulin or cells respond poorly to insulin." (PMID 36313695, 2022). "In our study, we did not investigate insulin levels, but we found that type I endometrial cancer patients, who were characterized by a high BMI, had a higher incidence of type II diabetes in comparison to type II endometrial cancer patients." (PMID 35053431, 2022). "Type 1 diabetes is characterized by a complete lack of insulin, whereas type 2 diabetes is characterized by peripheral tissue resistance to the effects of insulin." (PMID 35237647, 2022). "Adults with either type 1 or type 2 diabetes (on intensive insulin therapy or not) participated at 12 investigational sites in the United States." (PMID 35157505, 2022). "A major reason for this rapid market expansion was the speed with which insulin came to be used in type 2 diabetes, once known as non-insulin-dependent diabetes." (PMID 35275238, 2022). "The levels of insulin-stimulated GDR and NOX were ~40% and ~49% lower, respectively (all P<0.01), whereas the level of insulin-suppressed LOX was ~75-90% higher (all p<0.05) in men with type 2 diabetes compared to both obese and lean men." (PMID 36387850, 2022). "In fact, even in more recent studies, the quantification of insulin clearance reduction after oral vs. intravenous glucose administration in type 2 diabetes has not been extensively examined." (PMID 35169165, 2022). "Other HIIT-studies including both men and women with or without type 2 diabetes have reported beneficial effects on insulin sensitivity, VO2max and/or body composition in the pooled cohort." (PMID 36387850, 2022).
type 2 diabetes (continued). "Pseudin-2 stimulates insulin secretion from BRIN-BD11 cells through a mechanism involving the Ca2+-independent pathway and identifies [Lys18]-pseudin-2 as a peptide with potential to develop valuable insulin drugs as a treatment for type 2 diabetes." (PMID 36287990, 2022). "If insulin fails to control hepatic glucose production, this eventually ends with fasting hyperglycemia, which develops hepatic insulin resistance and type 2 diabetes (T2D)." (PMID 35159714, 2022). "This could explain why a majority of MUHO cases proceed to type 2 diabetes while pathogenesis in MHO is delayed significantly because these individuals still retain a normal glucose response and insulin sensitivity." (PMID 36143948, 2022). "On the other hand, insulin clearance, especially post-prandial, has been shown to be higher in subjects with type 2 diabetes than those without the disease." (PMID 36009446, 2022). "DPN and cognitive impairment in type 2 diabetes mellitus (T2DM) may share similar pathophysiologic changes, such as neurovascular mechanisms, insulin signaling and hyperglycemia and so on." (PMID 36324107, 2022). "This disorder occurs when the pancreas does not produce enough insulin, Type-1 Diabetes, or when the body cannot use the insulin effectively upon production, Type-2 Diabetes." (PMID 36140958, 2022). "The impact of the Gly482Ser polymorphism in PPARGC1A on body composition and glucose tolerance, as well as insulin sensitivity and secretion, was demonstrated in a Finnish study of nondiabetic offspring of patients with type 2 diabetes." (PMID 36558537, 2022). "Type 2 diabetes (non-insulin dependent) is more prevalent when compared to type 1 diabetes (insulin dependent)." (PMID 36527131, 2022). "Of note, other studies found neither alterations of myocellular sphingolipids nor relationships with insulin sensitivity in people who were obese and/or had type 2 diabetes." (PMID 34704121, 2022). "Persons with type 1 and type 2 diabetes treated with insulin, or type 2 diabetes not treated at home with insulin who have raised blood sugar in the hospital should have scheduled insulin while they are hospitalized to accommodate the need for high insulin." (PMID 35630061, 2022). "In fact, when directly compared with adults in the Restoring Insulin Secretion (RISE) study, youth with prediabetes and type 2 diabetes were more insulin resistant, had higher insulin secretion at baseline, and had faster rates of pancreatic β-cell decline over time." (PMID 36098974, 2022). "Only 84% of the overall population and 80% of the patients that did not skip their medications had type 2 diabetes; 86% of the overall population was prescribed insulin." (PMID 35619860, 2022). "Oleic acid contributes to insulin sensitivity, and its accumulation in muscle is lower in subjects with type 2 diabetes compared to those without." (PMID 35269531, 2022). "For example, studies in humans indicate a relationship between fat cell (adipocyte) size and the degree of insulin sensitivity; nonobese individuals with Type-2 diabetes have larger adipocytes than healthy controls." (PMID 35313696, 2022). "The routine use of continuous subcutaneous insulin infusion in inadequately controlled patients with type 2 diabetes is not recommended." (PMID 35288805, 2022). "Patients with Alström syndrome are more likely to develop childhood type 2 diabetes mellitus (T2DM) than patients with other syndromes, suggesting that ALMS1 may be of significance in the cell function and/or peripheral insulin signaling pathway." (PMID 36263163, 2022). "In a randomized trial of adults with type 2 diabetes, dietary advice to follow a low GI diet did not impact insulin sensitivity, but the disposition index, a measure of β-cell function, improved after 12 months." (PMID 35215537, 2022). "Therefore, the negative regulation of insulin secretion by UCP2 represents a strong link between obesity, β-cell dysfunction, and the development of type 2 diabetes." (PMID 35323702, 2022).
type 2 diabetes (continued). "During this trial, patients with Type 2 Diabetes were treated with insulin-NPs, observing an important reduction in insulin without hypoglycaemic side effects." (PMID 35457155, 2022). "Global O-GlcNAcylation levels were found augmented in type 2 diabetic patients, and OGT deletion specifically in skeletal muscle in mice improved insulin sensitivity and increased GLUT4 protein levels in gastrocnemius muscle of the KO mice in comparison to control mice." (PMID 35527999, 2022). "It appears when the pancreas does not produce enough insulin for the human body (type 1 diabetes) or when the insulin produced in the pancreas is not used effectively by cells (type 2 diabetes)." (PMID 36354482, 2022). "Maintenance of functional β-cells was likely achieved by a short-term intensive insulin therapy, which is recently reported as not providing benefit on islet β-cells in Type 2 diabetic (T2D) patients." (PMID 36142497, 2022). "The first-phase insulin response in the patients with type 2 diabetes was, however, not restored albeit the insulin response curve displayed a more marked first phase profile compared with baseline." (PMID 36531168, 2022). "DUAL I China, one of the DUAL trials, assessed efficacy/safety of insulin degludec/liraglutide (IDegLira) in Chinese adults with type 2 diabetes (T2D) not controlled by oral antidiabetic drugs (OADs)." (PMID 35762390, 2022). "To date, scarce information is available about the HHcy effect on insulin secretion, and the link between CBS activity and the setting of type 2 diabetes is still unknown." (PMID 35681432, 2022). "Our main finding is that this HIIT-protocol markedly improved insulin sensitivity with intact responses in obese men with and without type 2 diabetes." (PMID 36387850, 2022). "In the present study, the effect on in vitro antifungal activity in the presence and absence of human plasma by insulin and/or glucose, at levels analogous to those reported in type II diabetes, was determined." (PMID 35350119, 2022). "MBX-2982 shows positive results in phase II clinical trials of type 2 diabetes by successfully reducing postprandial glucose levels in type 2 diabetes mellitus (T2DM) patients, and increases insulin and incretin levels in a 4-week phase II clinical trial (ClinicalTrials.gov Identifier: NCT01035879)." (PMID 36396650, 2022). "Like in humans, where women are less likely than men to develop type 2 diabetes, female mice are more resistant to HFD than males and manifest improved glucose tolerance, with greater insulin sensitivity in liver, muscles and adipose tissue." (PMID 35250480, 2022). "We do not suggest a continuous glucose monitoring (continuous or on demand) rather than self-monitoring blood glucose in patients with type 2 diabetes on basal–bolus insulin therapy." (PMID 35288805, 2022). "The Centers for Disease Control and Prevention (CDC) states that over 1.5 million Americans per year are diagnosed with type 2 diabetes mellitus (T2DM), which is characterized by increased insulin resistance and blood glucose levels, and decreased insulin secretion." (PMID 35223263, 2022). "Likewise, low levels of IGFBP1 have been reported to predict the development of type 2 diabetes and IGFBP1 has been proposed as a potential marker of insulin sensitivity." (PMID 36498997, 2022). "In contrast, another study using 3-year administration of BPS reported no improvement in insulin sensitivity in patients with type 2 diabetes." (PMID 35557517, 2022). "Not only are IR mRNA levels decreased with type 2 diabetes compared to those controls without a history of type 2 diabetes, but the insulin-stimulated IR signaling response is also blunted in those individuals with type 2 diabetes." (PMID 35884888, 2022). "Our findings highlight the importance of controlling fasting insulin levels to mitigate the risk of PCOS, as well as screening for and long-term monitoring of type 2 diabetes in all women with PCOS, irrespective of BMI." (PMID 35771237, 2022).
type 2 diabetes (continued). "Type 1 diabetes refers to the fact that the pancreas produces no insulin whereas type 2 diabetes refers to the case where the pancreas produces an insufficient amount of insulin." (PMID 36601525, 2022). "Glucagon-like peptide-1 (GLP-1) and glucose-dependent insulinotropicpolypeptide (GIP) are incretin hormones with potent stimulatory effects onpostprandial insulin release.GLP-1 receptor (GLP-1R) agonism is an established therapeutic strategy for treatingand managing type 2 diabetes (T2D)." (PMID 35430298, 2022). "Type 2 diabetes mellitus (T2DM) and its subsequent complications are realized as a severe endocrine health concern, where the altered body metabolism occurs due to the imbalance in insulin levels." (PMID 35745030, 2022). "Six weeks of single-leg strength training (three times a week) increased skeletal muscle GLUT4 (∼40%) of the exercised leg in the elderly and non-obese type 2 diabetic patients, which helps to improve the insulin sensitivity." (PMID 35721547, 2022). "Type II diabetes is a state where there is plenty of blood glucose available, but the body is not able to utilize it due to insulin resistance in the body." (PMID 36258973, 2022). "In this large Dutch population-based study of men and women with and without type 2 diabetes, we observed 17% to 18% higher fasting insulin concentrations on Mondays compared to the other days of the week in men but not in women." (PMID 35575196, 2022). "In the context of glucose dyshomeostasis, such as during type 2 diabetes development, it is not fully inconsistent to observe both defective insulin secretion and increased fasting hyperglycemia and insulinemia." (PMID 35250480, 2022). "Participants included adults with type 2 diabetes (hemoglobin A1c [HbA1c] 6.5%-13.0%, not taking insulin, and no precluding health issues)." (PMID 36542382, 2022). "DM is categorized into two types, insulin-reliant, which is due to a lack of production of insulin in the human body termed type-1; however, in type-2 diabetes, either insulin is not produced by the human body or is incapable of utilizing insulin properly." (PMID 36186602, 2022). "It has been shown that it increases insulin sensitivity in the liver of healthy subjects and patients with type 2 diabetes without increasing the peripheral glucose consumption." (PMID 36012251, 2022). "Unlike patients with type 1 diabetes, adults with type 2 diabetes are characterized by a disease with progressive dysfunction of beta cells that evolve at a given moment with the need for insulin administration." (PMID 36556420, 2022). "It is well established that PP cows often exhibit symptoms similar to type 2 diabetes (T2DM), including elevated plasma free fatty acid concentrations and decreased sensitivity of tissue to the presence of insulin which plays a major role in the development of many metabolic disorders." (PMID 36153497, 2022). "In humans swith type II diabetes mellitus, 12-week treatment with pioglitazone increased insulin sensitivity and glucose utilization, but did not alter muscle mitochondrial function." (PMID 35315490, 2022). "In conclusion, this study proposes a model to determine the effects of amino acids on insulin secretion in people with or without type 2 diabetes." (PMID 36187117, 2022). "The testing of fungal susceptibility in the presence of plasma with and without the supplements glucose and/or insulin to simulate type II diabetes appears warranted in light of their sometimes adverse effect on the MIC of the antifungal agents." (PMID 35350119, 2022). "MAPK signaling pathway is believed to play an important role in the regulation of insulin secretion and type II diabetes mellitus (T2DM), and the secretion dose of insulin controls the lipid accumulation of precursor adipocytes and regulates the metabolism of adipose tissues." (PMID 36439361, 2022).
type 2 diabetes (continued). "Metformin treatment improved endothelial function, but not chronic, low‐grade inflammation in patients with type 2 diabetes treated with insulin." (PMID 36052760, 2022). "Majority of the 302 patients had type 2 diabetes, were non-smoker, centrally obese, non-insulin user and complicated with dyslipidemia, stage 2 CKD, and microalbuminuria (3.0 ± 1.1 mg/mmol)." (PMID 34195211, 2021). "For the most of patients with type 2 diabetes, there was no unambiguous evidence of benefit from insulin." (PMID 33655987, 2021). "The most common is type 2 diabetes (T2D), usually in adults, which occurs when the body becomes resistant to insulin or does not make enough insulin." (PMID 33799983, 2021). "Remarkably, mTORC1 has a negative connotation in type-2 diabetes research, because its activation by insulin mediates a negative feedback loop in insulin signaling, likely contributing to myocellular insulin resistance." (PMID 34265467, 2021). "In conclusion, mineralocorticoid receptor blockade does not appear to improve insulin sensitivity in individuals with type 2 diabetes." (PMID 34350730, 2021). "Three men, two in the GH treated group and one in the non-GH treated group, as well as two women in the non-GH treated group, were treated with insulin for type 2 diabetes." (PMID 34204309, 2021). "A substantial proportion of humans with type 2 diabetes fails to respond to rising PA with increasing insulin sensitivity." (PMID 34659107, 2021). "Hence, ci-Ins2 has an essential role in insulin secretion through sponging of the RNA binding protein TARDBP and is partly responsible for a defect in insulin secretion in the case of type II diabetes." (PMID 34449657, 2021). "Protein tyrosine phosphatase 1B (PTP1B), another key enzyme related to type 2 diabetes, works as a negative governor for the insulin signaling pathway by dephosphorylating both the insulin receptor and the downstream insulin receptor substrate proteins." (PMID 34707780, 2021). "Standard clinical indicators of IR may include fasting glucose and insulin to calculate HOMA-IR, a glucose tolerance test including measures of insulin, or a diagnosis of prediabetes or type 2 diabetes based on fasting glucose or HbA1c." (PMID 34684300, 2021). "The D’LITE study demonstrated that a culturally contextualized smartphone-based lifestyle intervention is capable of achieving meaningful weight reductions among Asian adults with type 2 diabetes and overweight or obesity who are not receiving insulin." (PMID 34081137, 2021). "Oxyntomodulin has been reported to enhance insulin secretion in short-term clinical studies in obese people with or without diabetes mellitus type II." (PMID 34577569, 2021). "Established insulin-treated non-obese type 2 diabetes shares many characteristics with type 1 diabetes, due to relatively greater insulin deficiency and lower insulin resistance than in type 2 diabetes associated with obesity." (PMID 34880011, 2021). "Thus, further studies are needed to examine the effect of chronic resistance exercise with exogenous administration of recombinant musclin on hyperglycemia, insulin resistance, and the muscle GLUT‐4 signaling pathway in rats with type 2 diabetes." (PMID 33955191, 2021). "Because the large islet mass needed to overcome insulin resistance is unlikely to be obtained with isolated islets, patients with type 2 diabetes are generally not considered candidates for islet transplantation." (PMID 33776933, 2021). "A larger variance in the change in systolic blood pressure was present in the individuals with type 2 diabetes, which likely explains the difference in response to MR blockade and not insulin per se." (PMID 34350730, 2021). "This combination therapy provides a more effective lowering of blood glucose with a low risk of hypoglycaemia and little or no weight gain in people with type 2 diabetes compared with insulin alone." (PMID 35602193, 2021).